GIPR (gastric inhibitory polypeptide receptor)
Diseases named in the same sentence as GIPR in open-access papers (continued):
Sharing a sentence is not in itself a finding about the gene and the disease.
Anxiety (4 papers, 2022 to 2023). Intense feelings of nervousness, tension, or panic often arise in response to interpersonal stresses. "Our findings demonstrated the novel role of GIPR in the brain and support that GIPR is a good potential target to treat chronic inflammatory pain and pain-related anxiety." (PMID 35712239, 2022). "These strongly suggest a potential role of GIPR in pain and anxiety modulation because neuroinflammation plays a key role in the maintenance of chronic pain and development of anxiety." (PMID 35712239, 2022). "In order to further confirm the regulation of GIPR on pain and anxiety, GIPR antagonist Pro3-GIP was simultaneous intraperitoneally injected at a dose of 50 nM/kg once daily for 10 days." (PMID 35712239, 2022). "It’s worth noting that the degree of pain and anxiety was almost restored to normal levels, which indicates that GIPR activation exerts excellent analgesic and anxiolytic effects." (PMID 35712239, 2022). "We also observed statistically significant association between GIPR rs1800437 GG genotype and BSPS scores in the abstinent alcohol-dependent patients as well as the association between GLP1R rs6923761 GG genotype and Zung anxiety scores in healthy controls." (PMID 35754710, 2022). "GIPR may be a suitable target for treatment of chronic inflammatory pain and pain-related anxiety." (PMID 35712239, 2022). "Additionally, GIPR and GLP-1R knockout mice showed impairment of synaptic plasticity and cognitive deficit; however, in another study, GIPR knockout mice showed extended lifespan, as well as increased exploratory and decreased anxiety-based behaviors, indicating a divergent effect of incretins." (PMID 35008973, 2022). "Statistically significant association between GIPR rs1800437 GG genotype and Brief Social Phobia Scale scores were observed in the abstinent alcohol-dependent patients, while GLP1R rs6923761 GG genotype was associated with Zung anxiety scores in healthy controls." (PMID 35754710, 2022). "The resulting data showed that activation of GIPR in the ACC attenuated pain and anxiety-like behaviors, potentially by inhibiting the excitatory synaptic transmission and inflammation in the ACC of mice models." (PMID 35712239, 2022). "Our study first reported that GIPR in the ACC was involved in chronic inflammatory pain and pain-related anxiety modulation." (PMID 35712239, 2022). "In summary, our study is the first to investigate the roles of GIPR in the ACC in the settings of chronic pain and pain-related anxiety." (PMID 35712239, 2022). "In order to determine the role of GIPR in CFA-induced chronic pain and anxiety-like behaviors, GIPR agonist D-Ala2-GIP was injected intraperitoneally (i.p.)at a dose of 25 nM/kg, once daily for 10 days." (PMID 35712239, 2022). "In order to investigate whether GIPR was related to CFA-induced chronic pain and anxiety-like behaviors, Western blot analysis was done to confirm the expression and protein molecular weight of GIPR in the ACC, hippocampus, and amygdala." (PMID 35712239, 2022). "Because of this, we speculated that the GIPR in the ACC may be involved in the regulation of chronic pain and pain-related anxiety." (PMID 35712239, 2022).
Impaired glucose tolerance (4 papers, 2022 to 2026). An abnormal resistance to glucose, i.e., a reduction in the ability to maintain glucose levels in the blood stream within normal limits following oral or intravenous administration of glucose. "We next studied the effects of GIPR agonism versus GIPR antagonism in a HFD‐induced obese mouse model with impaired glucose tolerance." (PMID 41287212, 2026). "A previous study revealed that GIPR(-/-) mice had impaired glucose tolerance and significantly reduced insulin gene expression and secretion compared with wild-type mice." (PMID 36860432, 2022). "Thus, the focus of our study was to comprehensively analyse the metabolic benefits and drawbacks of GIPR agonist versus GIPR antagonist treatment in a lean mouse model, and a high‐fat‐diet (HFD)–induced obese mouse model with impaired glucose tolerance." (PMID 41287212, 2026).
colorectal cancer (3 papers, 2022 to 2025). A primary or metastatic malignant neoplasm that affects the colon or rectum. "Moreover, the presence of GIPR was demonstrated in advanced colorectal cancer (CRC) and MC-26 and HT29 cells, two CRC cell lines." (PMID 38730608, 2024). "Colorectal cancers (CRC) express GIPR, which may facilitate GIPR ligand binding and subsequent proliferation of CRC cells via the modulation of pathways that support cancer progression." (PMID 36358930, 2022).
dyslipidemia (3 papers, 2022 to 2024). "The therapeutic effect of chronic GIPR agonism to treat dyslipidemia and thus to reduce the cardiovascular disease risk independently of body weight loss has not been explored yet." (PMID 37592302, 2023). "To increase our understanding of this relationship, we investigated the association of three GIPR SNVs, rs11672660, rs2334255 and rs10423928, with anthropometric measurements, selected metabolic parameters, and the risk of excessive body mass and metabolic syndrome (MS) in the Polish population." (PMID 36140702, 2022). "This study identified an unanticipated efficacy of chronic GIPR agonism to improve dyslipidemia and cardiovascular disease independently of body weight loss, indicating that treatment with acyl-GIP may be a novel approach to alleviate cardiometabolic disease." (PMID 37592302, 2023). "However, the therapeutic effect of GIP receptor (GIPR) agonism to treat dyslipidemia and reduce CVD-risk is not well defined yet and thus subject of intense ongoing investigations." (PMID 37592302, 2023).
Hyperinsulinemia (3 papers, 2018 to 2024). An increased concentration of insulin in the blood. "By potentiating postprandial insulin secretion and increasing blood insulin levels, there is some concern that pharmacological agonism of the GIPR signaling pathway could increase risk of hyperinsulinemia-driven cancers." (PMID 37250804, 2023).
Nausea (3 papers, 2022 to 2025). A sensation of unease in the stomach together with an urge to vomit. "It is noteworthy that GIPR agonism can also attenuate PYY mediated nausea in preclinical models, suggesting optimism for either dual or triagonist analogues of PYY, GLP-1, and GIP." (PMID 39963285, 2025). "Given that kaolin intake (i.e., pica behavior) can be viewed as a proxy of malaise and nausea in rats, these results could instead suggest that GIPR agonism may be more efficacious as an antiemetic than as an anti-nausea therapeutic." (PMID 40532005, 2025).
osteoporosis (3 papers, 2015 to 2024). A condition of reduced bone mass, with decreased cortical thickness and a decrease in the number and size of the trabeculae of cancellous bone (but normal chemical composition), resulting in increased fracture incidence. "Thus, although GLP-1R/GIPR agonists may result in significant weight loss, the co-administration of dual GLP-1R/GIPR agonists could potentially shield patients from concurrent osteoporosis by exploiting the inherent antiresorptive properties of GIP and GLP-1." (PMID 38725663, 2024). "Missense mutations in ADRB2, CNR2, FSHR, TSHR, CALCR, and GIPR genes were earlier associated with decreased BMD and osteoporosis in postmenopausal women as leading to amino acid substitutions and the possible receptor structure and/or function change." (PMID 39769358, 2024). "We found specific osteoporosis-linked SNPs in genes encoding key receptors involved in bone metabolism that are classified into rhodopsin (ADRB2, CNR2, MTNR1B, FSHR, TSHR, LGR4), secretin (CALCR, GIPR), and other T7M (WLS) receptor families." (PMID 39769358, 2024). "GIPR are expressed in bones and GIP directly affects bone metabolism, having a role in bone formation, as suggested by the reduction of bone formation parameters and high turnover osteoporosis in GIPR-deficient mice." (PMID 26075286, 2015).
overnutrition (3 papers, 2019 to 2024). An imbalanced nutritional status resulting from excessive intake of nutrients. "Altogether, our results identify GIPR/Rap1 signaling in the brain as a molecular pathway linking overnutrition to the control of neural leptin actions." (PMID 31403469, 2019). "Similarly, additional research identifies a molecular signalling pathway linking the gastric inhibitory polypeptide receptor (GIPR) with overnutrition via EPAC/Ras-related protein 1 (Rap1) in the brain." (PMID 35563589, 2022).
Parkinson disease (3 papers, 2016 to 2025). A progressive degenerative disorder of the central nervous system characterized by loss of dopamine producing neurons in the substantia nigra and the presence of Lewy bodies in the substantia nigra and locus coeruleus. "Neuroprotective effects of GIPR agonism have also been shown in animal models of Parkinson's Disease (PD)." (PMID 40024571, 2025). "Subsequent studies then showed that GIPR agonism has neuroprotective effects in mouse models for Alzheimer's and Parkinson's disease, ameliorates drug-induced emesis, and decreases body weight in rodents through centrally-mediated inhibition of food intake." (PMID 40024571, 2025).
pituitary adenomas (3 papers, 2023 to 2025). "The glucose-dependent insulinotropic polypeptide receptor (GIPR) is aberrantly expressed in about one-third of GH-secreting pituitary adenomas (GH-PAs) and has been associated with a paradoxical increase of GH after a glucose load." (PMID 37298217, 2023). "Another example is the expression of the GIPR in somatotropinomas (growth hormone-secreting pituitary adenomas)." (PMID 40024571, 2025). "Further studies are needed to establish the connection between oral food intake, GIP/GIPR axis, and the development of pituitary adenoma." (PMID 37344722, 2024).
adrenocortical cancer (2 papers, 2014 to 2024). "We showed the upregulation of the mRNA level of POMC, a precursor of ACTH, and MC2R in the GIP-treated and GIPR-expressing H295R adrenocortical cancer cell line." (PMID 25334044, 2014). "In this study, we transiently transfected the human GIPR expression vector into cultured human adrenocortical carcinoma cells (H295R) and treated them with GIP to examine the direct link between GIPR activation and steroidogenesis." (PMID 25334044, 2014).
alcohol (2 papers, 2022 to 2025). "The combined GIPR/GLP1R relationships with NAFLD, liver enzymes (ALT, GGT), binge drinking, alcohol misuse, and food liking outcomes show consistent protective relationships across both loci, with estimates from the GIPR locus providing particularly robust evidence." (PMID 40931165, 2025). "However, GIPR rs1800437 GC + CC and GC genotypes were significantly more frequent in hospitalized alcohol-dependent patients than in healthy controls (OR = 2.13, 95% CI = 1.17–3.87, p = 0.013 and OR = 2.21, 95% CI = 1.16–4.19, p = 0.015, respectively)." (PMID 35754710, 2022). "We conducted a pilot study to investigate the role of GLP1R rs10305420 and rs6923761 and GIPR rs1800437 in alcohol dependence and related psychosymptomatology in a cohort of hospitalized alcohol-dependent patients, abstinent alcohol-dependent patients, and healthy individuals." (PMID 35754710, 2022).
alcohol dependence (2 papers, 2022 to 2025). Physical and psychological dependence on alcohol. "According to our results, GIPR rs1800437 genotypes were associated with an increased risk of alcohol dependence." (PMID 35754710, 2022). "The current study aimed to investigate the potential association of GLP1R rs10305420 and rs6923761 and GIPR rs1800437 with alcohol dependence, as well as alcohol-related comorbid psychosymptomatology." (PMID 35754710, 2022). "Our findings indicated that GIPR rs1800437 genotypes were associated with an increased risk of alcohol dependence." (PMID 35754710, 2022). "Furthermore, GIPR mutations have been linked to alcohol dependence, suggesting its relevance in addiction biology." (PMID 40931165, 2025). "Our pilot study indicates that GIPR rs1800437 may play some role in susceptibility to alcohol dependence, as well as in alcohol-related psychosymptomatology symptoms." (PMID 35754710, 2022). "Concluding, our pilot study revealed a potential association between GIPR and alcohol dependence." (PMID 35754710, 2022). "It is crucial to mention that this is the first study that indicates the involvement of GIPR in alcohol dependence and alcohol-related comorbid psychosymptomatology." (PMID 35754710, 2022).
gestational diabetes (2 papers, 2024 to 2025). Carbohydrate intolerance first diagnosed during pregnancy. "Researchers have identified a set of SNPs in the GIPR gene as associated with T2D and gestational diabetes in a large cohort of patients from two ethnic groups." (PMID 41614819, 2025).
heart failure (2 papers, 2021 to 2025). Inability of the heart to pump blood at an adequate rate to meet tissue metabolic requirements. "For the five outcomes of heart failure (HF), BMI, C-reactive protein (CRP) levels, HDL-cholesterol (HDL-C) and triacylglycerols, there was evidence for Co-localisation also protects at both GIP and GIPR." (PMID 34505161, 2021).
Hypertension (2 papers, 2021 to 2024). The presence of chronic increased pressure in the systemic arterial system. "Furthermore, the E288G variant was associated with higher pulse pressure, while neither of the GIPR variants were associated with increased risk of hypertension." (PMID 34760890, 2021).
lung cancer (2 papers, 2017 to 2023). A malignant neoplasm involving the lung. "We show that the IL‐11 GIPR variant is an agonist cytokine that induces increased pSTAT3 signaling as compared with WT IL‐11 in the HeLa reporter cells and A549 human non‐small cell lung cancer cells (NSCLC)." (PMID 38023717, 2023). "Six genes showed particularly stronger expression pattern in lung cancer tissues, as compared to normal lungs, which demonstrated that these six genes (GABBR1, PDE4B, PDE4C, ADCY6, ADCY1 and GIPR) had more likelihood of being direct targets of miR-542-5p in lung cancers." (PMID 28927388, 2017).
medullary thyroid cancer (2 papers, 2024). "In a pathological context, human and rat medullary thyroid cancers display high GIPR expression levels compared to normal tissue, and massive overexpression of GIPR was described for neoplastic C cells of both rats and humans." (PMID 38730608, 2024).
mental disorder (2 papers, 2022 to 2025). A disease that has its basis in the disruption of mental process. "This suggests that GIPR may be a potential target to treat chronic pain and accompanying mental disorders." (PMID 35712239, 2022).
myocardial infarction (2 papers, 2020 to 2025). Gross necrosis of the myocardium, as a result of interruption of the blood supply to the area, as in coronary thrombosis. "Another strength of this study is the demonstration of an effect of a functional genetic variant in GIPR on CAD/myocardial infarction using the MR approach, suggesting an involvement of the GIP signalling pathway in the pathogenesis of CAD." (PMID 31974732, 2020). "The cardioprotective effect of GIPR deficiency further seems to be restricted to myocardial infarction and is not observed in mice with experimental heart failure induced by treatment with doxorubicin." (PMID 40024571, 2025).
sarcopenia (2 papers, 2023 to 2025). Progressive decline in muscle mass due to aging which results in decreased functional capacity of muscles. "GIP may promote adipogenic differentiation of muscle precursor cells, contributing to sarcopenia; thus, GIPR antagonism has been proposed as a potential therapeutic approach for sarcopenia management." (PMID 41515907, 2025). "However, GIP has non-negligible side effects on muscle cells, and GIPR antagonism could be used as a new treatment for sarcopenia." (PMID 41515907, 2025).
somatotropinomas (2 papers, 2023 to 2024). "We evaluated the steady-state level of GIPR in nine selected somatotropinomas and one normal pituitary gland using droplet digital PCR (ddPCR)." (PMID 37298217, 2023). "Together, these findings suggest that GIPR expression may be influenced by epigenetic regulation in somatotropinomas." (PMID 37298217, 2023). "Investigating, for instance, the presence of somatic alterations in KDM1A and their functional effects on GIPR expression, and more in general on the transcriptional profile of somatotropinomas, could be a promising target for short-term studies." (PMID 37298217, 2023). "In addition to the lack of the gsp oncogene, GIPR positive (GIPR+) somatotropinomas are characterized by a distinctive transcriptional profile and a higher frequency of genomic rearrangements and hypermethylation." (PMID 37298217, 2023).
adrenocortical tumor (1 paper, 2014). "These suggest that GIPR is not only ectopically expressed in the adrenocortical tumor, but also is activated by GIP after each meal, resulting in periodic cortisol secretion." (PMID 25334044, 2014). "Indeed, by immunofluorescence, we detected GIPR in specimens of adrenocortical tumor obtained from a patient with FD-CS one of us (Y.T.)and his colleagues had reported previously." (PMID 25334044, 2014).
aortic atherosclerosis (1 paper, 2024). A atherosclerosis that involves the aorta. "Loss of GIPR induced aortic atherosclerosis and inflammation in ApoE−/−:Gipr−/− high fat diet-fed mice despite a reduced weight gain and preserved glucose homeostasis compared to ApoE−/−:Gipr+/+ mice, further confirming the anti- inflammatory role of GIP in atherosclerosis." (PMID 39834741, 2024).